BRCA1 (BRCA1 DNA repair associated)
Diseases named in the same sentence as BRCA1 in open-access papers (continued):
Sharing a sentence is not in itself a finding about the gene and the disease.
breast cancer (continued). "Since the discovery of the BRCA1 and BRCA2 genes, a total of 1,643 and 1,856 distinct variants have been reported in the Breast Cancer Information Core (BIC) Database for BRCA1 and BRCA2 as of April 2007." (PMID 18284688, 2008). "BRCA1 was the first identified breast cancer susceptibility gene and was localized to 17q21 by positional cloning more than 15 years ago." (PMID 18241344, 2008). "In hereditary breast carcinoma, mutations in highly penetrant genes such as BRCA1 or BRCA2 confer a relatively high risk for developing breast carcinoma, though this risk accounts only for about 5 to 10% of all breast carcinoma cases." (PMID 18423013, 2008). "In women with early-onset breast carcinoma unselected for family history, the prevalence of BRCA1 mutations is estimated to be between four and nine percent." (PMID 18431501, 2008). "Mutation frequencies reported in the literature indicate that about 10% of all women with breast cancer diagnosed before the age of 50 years have a germline mutation in BRCA1, BRCA2, ATM or CHEK2." (PMID 17428320, 2007). "Many of the DNA sequence variants identified in the breast cancer susceptibility gene BRCA1 remain unclassified in terms of their potential pathogenicity." (PMID 18036263, 2007). "• The BRCA data contains 3,170 genes and was collected from 15 patients with hereditary breast cancer, who had mutations either of the BRCA1(n = 7) or the BRCA2 gene (n = 8)." (PMID 17257426, 2007). "BRCA1, a familial breast and ovarian cancer susceptibility gene, encodes nuclear phosphoproteins that function as tumor suppressors in human breast cancer cells." (PMID 19936073, 2007). "In BRCA1, the common Jewish 185delAG and 5382insC mutations are outside the low breast cancer risk central region, and 5382insC is within the low ovarian cancer risk region." (PMID 17213823, 2007). "Risk-reducing mastectomy (RM) is one option for breast cancer risk reduction that is offered to women who learn they are carriers of a BRCA1/2 gene mutation." (PMID 17341306, 2007). "(B) BRCA1, a gene deleted in about 5% of women with breast cancer, encodes a protein that interacts with many other proteins." (PMID 17233903, 2007). "Women carrying pathogenic gene mutations in either BRCA1 or BRCA2 are at significantly increased lifetime risk of up to 80% for developing breast cancer." (PMID 17324252, 2007). "The breast cancer susceptibility gene, BRCA1, is implicated in multiple cellular processes including DNA repair, the transactivation of genes, and the ubiquitination of proteins; however its precise functions remain to be fully understood." (PMID 17511879, 2007). "Mutations in high-penetrant genes such as BRCA1 (breast cancer 1, early onset) and BRCA2 account for only a small proportion of this hereditary component, suggesting an important but yet-to-be-detected role for low-penetrant single nucleotide polymorphisms." (PMID 17598882, 2007). "PIK3R1 and PLCG1 are involved in intracellular signaling cascades and their differential regulation is known to be involved in tumorigenesis, while POU2F1 interacts with several known breast cancer-associated proteins (i.e. BRCA1, BARD1 and PARP1)." (PMID 17280605, 2007). "Breast density has been shown to predict risk among women with a genetic predisposition for breast cancer, including women carrying BRCA1 or BRCA2 mutations." (PMID 17949495, 2007). "Loss of BRCA1 is associated with a more aggressive phenotype in sporadic breast cancer and concomitant loss of FHIT and BRCA1 alleles has also been reported in a number of repair-deficient cancers including breast cancer and ovarian cancers." (PMID 17164758, 2007). "In the Breast Cancer Linkage Consortium (BCLC) families, by age 70 years, BRCA1 carriers had a breast cancer risk of 71% (95% CI 53–82%) and an ovarian cancer risk of 47–63%." (PMID 17213823, 2007).
breast cancer (continued). "By age 70 years, for BRCA1 carriers, breast cancer risk was 69% (SE 5%) and ovarian cancer risk was 46% (SE 6%), and for BRCA2 carriers, breast cancer risk was 74% (SE 8%) and ovarian cancer risk was 12% (7%)." (PMID 17213823, 2007). "For example, an RR of 7.7 (95% CI 2.6–23) for breast cancer risk was found in BRCA1 carriers born from 1960 on, compared to those born before 1920." (PMID 17213823, 2007). "Classification of a hereditary family history of breast cancer in our sample primarily represented the presence of a BRCA1 mutation or a BRCA2 mutation." (PMID 17949495, 2007). "We have previously shown that tumors expressing the CK5/6 marker are associated with germline BRCA1 mutations based on data on unselected breast cancer cases from a single institution (Jewish General Hospital, JGH)." (PMID 17650314, 2007). "Female BRCA1/2 carriers are told they have an estimated lifetime risk of breast cancer between 50% and 85%." (PMID 17341306, 2007). "Both data sets have immunohistochemistry data of estrogen receptor (ER) status, which is known to play important role in breast cancer biology, e.g., BRCA1 mutation, lymphocytic infiltration, and early occurrence of distant metastasis." (PMID 18030330, 2007). "A significant proportion of inherited breast cancer is caused by mutations in the BRCA1 and BRCA2 tumour suppressor genes which disrupt their role in cellular DNA repair, cell cycle control, apoptosis, and tumour suppression." (PMID 18036263, 2007). "Several previous studies have evaluated the risk of breast cancer associated with OC use among women with a family history of breast cancer or those carrying germline defects in BRCA1 or BRCA2." (PMID 17553133, 2007). "Certain tumour characteristics are characteristically seen in breast cancers due to a BRCA1 gene mutation and also to a lesser degree in BRCA2 gene carriers." (PMID 17697367, 2007). "Genetic, reproductive, and environmental factors have all been suggested to influence breast cancer risk in BRCA1 mutation carriers (reviewed in Narod and Offit (2005))." (PMID 17213827, 2007). "In contrast, the loss of BRCA1 expression appears to be an important mechanism driving tumour formation in sporadic breast cancer cases." (PMID 17663789, 2007). "A larger case-only study found that increased physical activity and lack of obesity in adolescence were associated with significantly delayed breast cancer onset in BRCA1 and BRCA2 carriers." (PMID 17213823, 2007). "Out of all breast cancers, 5 to 10% can be attributed to germline mutations in familial high-risk genes such as BRCA1 or BRCA2 that result in a lifetime breast cancer risk of about 45 to 65%." (PMID 17428320, 2007). "Further studies are required for the evaluation of the specificity and predictive value of aberrant methylation in DL fluid for future breast cancer development in BRCA1/2 mutation carriers." (PMID 17324252, 2007). "The highest prevalence of CHEK2 1100delC has been reported in familial non-BRCA1/2 families also harboring colon cancer cases (18%) and in some highly selected high-risk breast cancer families (9–11%)." (PMID 17705858, 2007). "A high proportion of BRCA1 tumors exhibit the basal-like phenotype and germ-line BRCA1 mutations result in breast cancers that are more likely to be basal-like in nature." (PMID 17650314, 2007). "Less than 40% of familial breast cancer can be attributed to mutations in the high-risk genes BRCA1 and BRCA2 despite their high penetrance." (PMID 17697391, 2007). "Hereditary ovarian and breast cancers are based on germline mutations in the same cancer susceptibility genes, BRCA1 and BRCA2, suggesting similar pathways of oncogenesis at least for a fraction of these diseases." (PMID 17245339, 2007).
breast cancer (continued). "Numerous advances in our understanding of genetic susceptibility to breast cancer have been made over the past decade, most notably the discovery of BRCA1 in 1994 and BRCA2 in 1995." (PMID 17916242, 2007). "For example, it has been demonstrated that about 15–30% of western breast cancer women aged less than 35 years are likely to have germ-line BRCA1 or BRCA2 mutations." (PMID 18053234, 2007). "The structure and regulation of the BRCA1 promoter has been of particular interest due to the association of decreased BRCA1 gene transcription with the development of sporadic breast cancer." (PMID 17663789, 2007). "Inactivating and truncating mutations of the nuclear BRCA1-interacting protein 1 (BRIP1) have been shown to be the major cause of Fanconi anaemia and, due to subsequent alterations of BRCA1 function, predispose to breast cancer (BC)." (PMID 17504528, 2007). "An impaired cellular response to DNA damage is a plausible mechanism whereby BRCA1 mutation carriers are at increased risk of breast cancer." (PMID 17213827, 2007). "The inheritance of a deleterious mutation in the breast cancer susceptibility gene, BRCA1, has been associated with a lifetime risk of breast cancer of between 45 and 87%." (PMID 17213827, 2007). "One FIGO stage IIIc ovarian cancer was diagnosed during diagnostic surgery in a 52-year-old carrier of a BRCA-1 mutation with a history of breast cancer." (PMID 16495917, 2006). "BRCA1 and BRCA2 are considered to be the breast cancer genes, but BRCA1 is also associated with ovarian cancer." (PMID 16721370, 2006). "BACH1 (BRCA1-associated C-terminal helicase 1; also known as BRCA1-interacting protein 1, BRIP1) is a helicase protein that interacts in vivo with BRCA1, the protein product of one of the major genes for hereditary predisposition to breast cancer." (PMID 16430786, 2006). "Inherited predisposition to breast cancer is well established in BRCA1 (MIM# 113705) and BRCA2 (MIM# 600185) mutation carriers." (PMID 16622469, 2006). "The induction of BRCA1 was associated with morphologic evidence of mammary differentiation and a reduced susceptibility to 7,12-dimethylbenz[a]anthracene-induced mammary tumours." (PMID 16434996, 2006). "ATM gene's contribution to breast cancer risk was previously evaluated in the context of high-risk families, in BRCA1/2 mutation carriers, and in average risk populations." (PMID 16622469, 2006). "Treatment guidelines of breast cancer occurring in BRCA1/BRCA2 mutation carriers or in patients with an increased familial risk are not well established." (PMID 16404417, 2006). "The six coding variants causing an amino acid change were genotyped in an independent European Caucasian validation group consisting of 46 unrelated breast cancer cases originating from high-risk non-BRCA1/2 families." (PMID 17010193, 2006). "Breast cancer had developed in 59 of the females with BRCA1 mutations: 5/12 (41.7%) of those with the G/G genotype, 27/43 (62.8%) of those with the G/T genotype and 27/ 41 (65.8%) of those with the T/T genotype." (PMID 16563154, 2006). "Yet, only 20–40% of familial inherited breast cancer risk is conferred by BRCA1/2 mutations, and clearly other genes are involved in familial breast cancer clustering." (PMID 16622469, 2006). "Esc4 contains several copies of the BRCT motif, originally identified in the human breast cancer susceptibility gene, BRCA1." (PMID 17094803, 2006). "The existence of dominant predisposition alleles/mutations, conferring a high breast cancer risk, has been confirmed with the discovery of BRCA1 and BRCA2." (PMID 16672066, 2006). "Evidence-based screening guidelines are needed for women under 40 with a family history of breast cancer, a BRCA1 or BRCA2 mutation, or other risk factors." (PMID 16800895, 2006). "Epidemiological studies indicate that BRCA1 mutation carriers have a lifetime risk of breast cancer that is on the order of 60–80%." (PMID 17018160, 2006).
breast cancer (continued). "There was evidence that increasing number of live births was associated with a decreasing risk of breast cancer in BRCA1 and BRCA2 mutation carriers combined." (PMID 17187672, 2006). "Oestradiol increased proliferation in the breast epithelium from women carrying mutations in the BRCA1/2 genes, those otherwise at increased risk and those at population risk of breast cancer." (PMID 16538216, 2006). "A significant proportion of these patients (20–45%) have a mutation in the breast cancer genes, BRCA1 or BRCA2." (PMID 16404418, 2006). "Germline mutations in one allele of the BRCA1 or BRCA2 genes significantly increase the risk of developing early-onset breast cancer." (PMID 16846527, 2006). "A large proportion of familial breast cancer (<40%) can be attributed to mutations in the high-risk genes BRCA1 and BRCA2." (PMID 16762046, 2006). "The Tyrer-Cuzick algorithm was applied to the cohort to test its ability to predict future breast cancer and positive BRCA1 or BRCA2 mutation tests, with considerable success." (PMID 16507150, 2006). "While the loss of BRCA1 expression or function is linked to breast cancer, the role of upregulation of either BRCA gene in preventing cancer is unclear." (PMID 16434996, 2006). "Although BRCA1 mutations have been described also in men with breast cancer, the presence of germ-line mutations in the BRCA1 gene does not seem to convey a significantly increased risk for MBC." (PMID 16764716, 2006). "In particular, increasing parity has been shown to be protective for breast cancer in the general population in many studies, but its effect among BRCA1 and BRCA2 mutation carriers is still under debate." (PMID 17187672, 2006). "Shortly after the cloning of the breast cancer susceptibility genes BRCA1 and BRCA2, three specific mutations in BRCA1 and BRCA2 were found to be 20 times more common in individuals of Ashkenazi Jewish descent than in the general population." (PMID 17102813, 2006). "Approximately 5% of all cases of breast cancer are associated with inherited predisposition syndromes and about half of these are attributable to mutations in the BRCA1 and BRCA2 genes." (PMID 16538216, 2006). "To confirm that loss of function was responsible for the effects of the BRCA1 mutant, we transfected cultures of breast cancer cell lines with BRCA1 siRNA." (PMID 16417649, 2006). "Further deficiencies included the equal weighting given to male and female breast cancers and the inability to input bilateral breast cancer or other tumours associated with BRCA1/2 mutation, namely prostate and pancreatic cancers." (PMID 17016486, 2006). "Breast cancer risk in the general population is closely related to reproductive history, and reproductive factors are therefore strong candidates for modifiers of breast cancer risk in BRCA1 and BRCA2 mutation carriers." (PMID 17187672, 2006). "BRCAPRO over-predicted the number of BRCA1 mutations among both unaffected individuals and breast cancer cases." (PMID 16417652, 2006). "We now report that both I3C and genistein induce the expression of both breast cancer susceptibility genes (BRCA1 and BRCA2) in breast (MCF-7 and T47D) and prostate (DU-145 and LNCaP) cancer cell types, in a time- and dose-dependent fashion." (PMID 16434996, 2006).
breast cancer (continued). "One ovarian cancer (FIGO stage IIIc) was diagnosed at diagnostic laparoscopy after abnormal findings at the first surveillance visit in a 52-year-old patient with a history of breast cancer and carrier of a BRCA-1 mutation." (PMID 16495917, 2006). "The lifetime breast cancer risk for BRCA2 mutation carriers approaches that of BRCA1 carriers: however, disease onset has been documented to be at a later age." (PMID 17018160, 2006). "Various reproductive factors have been shown to exert different effects on the risk of breast cancer among BRCA1 and BRCA2 mutation carriers." (PMID 16563180, 2006). "The breast cancer susceptibility gene BRCA1 is involved in the repair of double-strand breaks induced by ionizing radiation and chemotherapy drugs." (PMID 16417649, 2006). "The complete sequence of all exons and flanking intronic sequences were analyzed in DNA samples from 54 individuals affected with breast cancer from non-BRCA1/2 high-risk French Canadian breast/ovarian families." (PMID 17010193, 2006). "Inheritance of a truncating mutation of the breast cancer predisposition gene BRCA1 has been reported to carry a lifetime risk of breast cancer of between 50 and 80%, with age at onset of first malignancy varying from the 2nd to the 8th decade." (PMID 16563154, 2006). "RAD51 interacts directly or indirectly with a number of proteins implicated in breast cancer, such as BRCA1 and BRCA2." (PMID 16762046, 2006). "About 6% of breast cancer cases in women < 50 years of age are due to germline mutations in the BRCA1 or BRCA2 breast and ovarian cancer susceptibility genes." (PMID 16800895, 2006). "Andrieu and colleagues found that BRCA1 mutation carriers who had their first full-term pregnancy after the age of 30 years had a significantly lower risk of developing breast cancer." (PMID 17187672, 2006). "Most breast cancer in BRCA1 mutation carriers arises in so-called 'basal' cells that stain positive for certain cytokeratins." (PMID 17187672, 2006). "Mutations of BRCA1 occur in at least 10% of inherited breast cancers, but are very rare in sporadic breast cancer." (PMID 17047656, 2006). "Against these, however, are data showing that incidence of breast cancer in BRCA1 and BRCA2 mutation carriers is altered by endocrine risk modifiers such as pregnancy." (PMID 16538216, 2006). "A recent meta-analysis of 22 population-based studies of breast and ovarian cancer estimated the risk for breast cancer by age 70 years in BRCA1 and BRCA2 carriers to be 65% and 45%, respectively." (PMID 16417652, 2006). "The breast cancer risk by age 70 years was estimated to be 72% in BRCA1 mutation carriers and 75% in BRCA2 mutation carriers." (PMID 16417652, 2006). "In families with BRCA2 mutations, female breast cancer was more frequent in the first and second-degree relatives compared to the families with wild type BRCA1/2 (31.9% vs. 8.0% p = 0.001)." (PMID 16764716, 2006). "Nipple aspiration was performed on 33 high-risk women (defined as having a 5-year Gail model index of more than 1.7, a personal or family history of breast cancer, and/or a BRCA1 or BRCA2 germline mutation) to identify ductal orifices for lavage procedures." (PMID 16280052, 2005). "When hereditary predisposition to breast cancer is being assessed, it is important to consider the impact of the age-related penetrance of the BRCA1 and BRCA2 genes." (PMID 16079000, 2005). "A recent meta-analysis including 22 studies, revealed an average cumulative risk of 65% for breast cancer and 39% for ovarian cancer in BRCA1 mutation carriers by age 70 years." (PMID 16052221, 2005). "As these cases are so rare, the long-term risk of breast cancer following preventive mastectomy in BRCA1/2-positive individuals is likely to be very low." (PMID 16079000, 2005).